GAST (gastrin)
Diseases named in the same sentence as GAST in open-access papers (continued):
Sharing a sentence is not in itself a finding about the gene and the disease.
gastric cancer (continued). "Our data extend our knowledge on the mechanism of curcumin in retarding gastric cancer progression, and could possibly give rise to new applications of curcumin based on its effects in regulating gastrin and gastric pH." (PMID 28781948, 2017). "The objective of this study was to investigate whether curcumin regulates gastrin‐mediated acid secretion in suppressing gastric cancer." (PMID 28781948, 2017). "This is supported by the increased serum gastrin levels in high‐level gastric cancer patients." (PMID 28781948, 2017). "Results from previous studies have suggested that sex hormones, including estrogens, might inhibit the development and progression of gastric cancer by increasing an individual’s resistance to inflammation and inhibiting production of gastric acid and gastrin." (PMID 26727146, 2016). "It has been suggested that Reg1 may be a critical downstream gene in the process of gastrin stimulated gastric cancer development." (PMID 25621062, 2015). "For example, coffee contains some phenolic compounds such as chlorogenic acid and caffeic acid, which have anti-cancer properties, and coffee can stimulate the release of gastrin, which may be involved in the development of gastric cancer." (PMID 26023935, 2015). "In gastric cancer, targeting the gastrin peptide has been studied in a multicenter, phase II trial." (PMID 26579545, 2015). "Furthermore, gastrin was found to reduce SLC4A1 expression in gastric cancer cells by eliciting its protein degradation." (PMID 24795638, 2014). "However, a subset of patients infected with H. pylori show mild-moderate increases in circulating levels of amidated gastrin, and thus a role for gastrin in gastric cancer was suggested, given its known role as a growth factor for the stomach." (PMID 24216700, 2013). "It has been reported that gastrin promotes the development of gastric cancer." (PMID 23110168, 2012). "We have shown that exogenous administration of gastrin-17 (G17) peptide could promote AGS gastric cancer cells proliferation and upregulate RegIα expression, but whether the gastrin is associated with the expression of RegIα in vivo remains unclear." (PMID 21949663, 2011). "It is presumed that hypergastrinemia might be a critical driver of gastric carcinogenesis in Hp-negative AIG, where parietal cell destruction-induced hypochlorhydria elevates serum gastrin, significantly increasing risks for proximal (OR = 6.1) and intestinal-type (OR = 3.8) gastric cancers." (PMID 41210850, 2025). "Interestingly, we reported that deletion of Smox in C57BL6 mice and in cancer-prone transgenic FVB/N mice overexpressing the human gastrin gene reduces the development of gastritis and gastric carcinoma, respectively, demonstrating that SMOX activity mediates H. pylori pathogenesis." (PMID 41282235, 2025). "Gastric cancer occurrence may hopefully be prevented by H. pylori eradication at a young age, and by the reduced use of inhibitors of acid secretion and use of a gastrin antagonist in those with previous long-term H. pylori infection and those with autoimmune gastritis." (PMID 37941554, 2023). "Thus, it is hypothesized that a lower level of SST leads to a higher level of gastrin, which increases gastric cancer occurrence." (PMID 35650297, 2022). "Whether gastrin has a dominant role in the development of gastric carcinoma has been under debate." (PMID 34976177, 2022). "Moreover, gastrin could regulate autophagy of gastric cancer cells through the AMPKα/Ras/Raf/MEK/ERK pathway and plays a procancer role." (PMID 33937399, 2021). "The neglection of the importance of gastrin in gastric carcinogenesis may have serious consequences, since the incidence of gastric cancer could be markedly reduced by early eradication of H. pylori before development of oxyntic atrophy, which may be achieved by testing and treating young adults." (PMID 34207192, 2021).
gastric cancer (continued). "Moreover, gastrin can regulate the growth and differentiation of gastric epithelial cells, which might be relevant in the pathogenesis of gastric cancer." (PMID 30611258, 2019). "Interestingly, Goetze and co-workers showed that a majority of gastric carcinomas localized to different parts of the stomach, expressed both gastrin and the gastrin receptor that could indicate a stimulatory autocrine loop." (PMID 30567376, 2018). "In the current study, we report that gastrin induces autophagy and increases cell migration and survival in vitro, and suggest that these molecular mechanisms may contribute to tumor progression of gastric cancer cells." (PMID 28109268, 2017). "Furthermore, experiments in GF and CV gastrin-overexpressing mice demonstrated that the presence of the microbiota accelerated H. pylori-induced stomach cancer in this model, and that specific bacterial taxa from these H. pylori infected mice were sufficient to induce disease acceleration." (PMID 29049360, 2017). "Additionally, sCLU decreased the cytotoxicity of cisplatin on gastric cancer cells, similarly as gastrin, and both might be involved in treatment resistance." (PMID 28902909, 2017). "Thus, we hypothesized that gastrin may be involved in the activation of autophagy in human gastric cancer cells." (PMID 28109268, 2017). "However, the role of gastrin in adenocarcinoma is still not completely understood, and whether gastrin acts as an autocrine/paracrine growth factor in gastric carcinoma is unclear." (PMID 28109268, 2017). "To identify additional cis-acting elements within the Reg1 gene that may participate in transcriptional regulation and the effects of gastrin on expression of Reg1, we investigated whether introns of Reg1 gene can increase its expression and bind to transcription factors in gastric cancer cells." (PMID 25621062, 2015). "Gastrin knockout mice are achlorhydric, favouring a bacterial gastric overgrowth, and chronic bacterial gastric infections lead to gastric metaplasia which may progress into gastric cancer." (PMID 21418558, 2011). "Interestingly, studies during the past two decades have also demonstrated that the gastrointestinal (GI) peptide hormone gastrin might contribute towards the pathobiology of gastric cancers." (PMID 20637111, 2010). "Helicobacter pylori infection is a unique risk factor for gastric cancer, and some studies found that Helicobacter pylori increased EMT in gastric cancer through its cooperative network involving MMP-7, VEGF, and gastrin." (PMID 38737444, 2024). "Gastrin, released into the medium by cancer cells and binding to CCK-BR on cancer cells, stimulated the proliferation, migration, and invasion of gastric cancer cells in vitro." (PMID 34976177, 2022). "In conclusion, we provided direct evidence and possible mechanism of gastrin/CCK-BR signaling in the initiation and progression of gastric cancer." (PMID 34976177, 2022). "The pcDNA3.1/gastrin vector was used to transfect the gastric cancer AGS and SGC-7901 cells to establish stable gastrin-overexpressing cell lines." (PMID 34976177, 2022). "Investigators have studied the expression of gastrin and the CCK-BR from resected human gastric cancers and found that most expressed CCK-BRs and gastrin." (PMID 34926305, 2021). "Two separate murine gastric cancer cells were evaluated for expression of CCK-BR, PD-L1 receptors and gastrin peptide in vitro." (PMID 34926305, 2021). "We found that both murine gastric cancers (YTN and NCC) expressed CCK-BRs and when YTN tumor bearing mice were treated with a gastrin vaccine, the tumor growth rate and metastases significantly decreased." (PMID 34926305, 2021). "There is an indication that gastrin and released factors by ECL cells promote the proliferation of gastric cells, including cell precursors, which is also relevant for gastric cancer pathogenesis." (PMID 34440074, 2021).
gastric cancer (continued). "In the current investigation, we studied the role of the gastrin-CCK-BR pathway in vitro and in vivo as well as the expression of the CCK-BR in a human gastric cancer tissue array." (PMID 34926305, 2021). "From what is written above, it should be evident that gastrin is a complete carcinogen for the ECL cell, and thus for gastric cancer." (PMID 32796591, 2020). "The central role of gastrin and the ECL cell in gastric cancer most probably has implications for other cancers and gives rise to improved prophylaxis and treatment." (PMID 32796591, 2020). "Gastrin (GAST) is hormonal regulator of gastric acid secretion and promotes the carcinogenesis of gastric cancer." (PMID 33224866, 2020). "These factors together with the fact that a proportion of gastric carcinomas display markers of NE and ECL cell differentiation, suggestive of ECL cell origin, result in gastrin becoming of interest in gastric carcinogenesis." (PMID 28980157, 2018). "With the development and improvement of gene transfer technology, investigators created a variety of transgenic and knockout/knockin mouse models of gastric cancer, such as INS-GAS mice and gastrin knockout mice." (PMID 27713138, 2017). "We have repeatedly shown that gastric carcinomas, especially of diffuse type, express NE markers and more specifically ECL cell markers, which incriminate gastrin in the pathogenesis." (PMID 28144230, 2017). "The proliferative efficiency of gastric cancer cell line SGC7901 decreases significantly following Reg1 knock-down and incubation with gastrin." (PMID 25621062, 2015). "We used the gastric cancer cell line AGS, permanently transfected with the CCK2 receptor (AGS-GR) to study gastrin stimulated expression of PAI-2 and Reg1 reporter constructs when PSMB1 was knocked down by siRNA." (PMID 23544109, 2013). "The case of a Spanish family whose members had a missense mutation in one of the genes coding for the proton pump supports the theory that gastrin and ECL cells play important roles in gastric carcinogenesis, and that ECL cell NETs are precursors of gastric cancer." (PMID 37941554, 2023). "The gastrin mRNA content in metastatic lymph nodes was higher in patients with gastric cancer than in primary gastric cancer and adjacent nontumor tissues." (PMID 34976177, 2022). "To determine whether the pro-invasive and -metastatic effects of gastrin involve MMP-2 and VEGF in gastric cancer cells, we detected the mRNA and protein expression and secretion of MMP-2 and VEGF in gastrin-overexpressed and gastrin-knocked down cells." (PMID 34976177, 2022). "The lack of PTGER3 leads to abnormal secretion of gastrin and gastric acid and accelerates the occurrence of gastric cancer." (PMID 34646828, 2021). "Unlike the physiologic expression of gastrin in the G cells of the stomach antrum, the gastrin gene also becomes overexpressed de novo in non-endocrine epithelial cells of gastric cancer where it can stimulate growth in an autocrine fashion." (PMID 34926305, 2021). "Netazepide, a specific gastrin antagonist with few if any side effects and proven efficacy in the treatment of gastric NETs, has not been tried in the treatment of gastric cancers although gastrin receptors are frequently expressed." (PMID 34202596, 2021). "The gastrointestinal peptide gastrin has been shown to stimulate growth of gastric cancer in a paracrine and autocrine fashion through the cholecystokinin-B receptor (CCK-BR), a receptor that is expressed in at least 56.6% of human gastric cancers." (PMID 34926305, 2021). "Gastric carcinoma tissues expressing both gastrin and CCK2R have a poorer prognosis than those negative for both." (PMID 32210918, 2020). "Multiple oncogenic signaling pathways (gastrin-CREB, NGF-neurotrophin, PDGF, EGFR, ERK, ERBB4, FGFR1, RAS, VEGFR2 and RAF/MAP kinase) known to be active in aggressive gastric cancers were strikingly diminished in gastric cancers with low DOK6 expression." (PMID 29872697, 2017).
gastric cancer (continued). "Furthermore, gastric cancer cell lines expressed and secreted CLU upon stimulation with stressors like gastrin and cisplatin." (PMID 28902909, 2017). "Moreover, previous research proved that the gastrin and CCK-BR loop blockage inhibited gastric cancer cells proliferation." (PMID 27518872, 2016). "The five intron fragments of Reg1 were also randomly labeled with digoxin as a probe, and nuclear proteins of gastric cancer cells were extracted following treatment with or without gastrin." (PMID 25621062, 2015). "It was previously reported that a C-rich region of the proximal promoter sequence of Reg1 is required for gastrin-stimulated expression in gastric cancer cell line, AGS, and that the expression of Reg1 is controlled through separate promoter elements −2111 and −104 bp by gastrin." (PMID 25621062, 2015). "To investigate whether SIK1 participates in regulation of the CRTC2-CREB axis also in gastric cancer cells, we examined the subcellular localization of CRTC2 protein upon gastrin treatment in AGS-GR cells." (PMID 25384047, 2014). "In gastric cancer, both upregulation and downregulation of SLC4A2 has been reported, and this was proposed to reflect that its expression is regulated by gastrin, the expression of which varies between different gastric cancers and cancer stages." (PMID 24795638, 2014). "Several studies have shown that both hypergastrinemia and the lack of Gastrin contribute to the pathogenesis of gastric cancer." (PMID 21418558, 2011). "Similarly, we also observed that in gastric cancer cell line AGS, IL1B induced Smad 7, inhibits the phosphorylation of Smad 3 and subsequently interferes with gastrin expression." (PMID 21445336, 2011). "In addition, significantly high levels of plasma gastrin has been reported in patients with gastric cancer, with high expression of gastrin and its receptor (CCK2R) in gastric cancer cell lines." (PMID 20637111, 2010). "Quantitative detection also found that gastrin mRNA levels in metastatic lymph nodes were 11 times higher than that in primary gastric cancer and 30 times that in adjacent nontumor tissues in patients with gastric cancer." (PMID 34976177, 2022). "However, whether the gastrin/CCK-BR axis is crucial for the invasion and metastasis of gastric cancer cells remains unclear." (PMID 34976177, 2022). "Although non-invasive detection of precancerous stomach lesions remains an attractive strategy to decrease gastric mortality, the estimated sensitivities of stand-alone pepsinogen tests or its combination with gastrin-17 for population-based gastric cancer screenings are not ideal." (PMID 35885649, 2022). "Furthermore, we detected gastrin mRNA content in human gastric cancer tissues, metastatic lymph nodes, and adjacent nontumor tissues." (PMID 34976177, 2022). "Moreover, the target cell of gastrin, the enterochromaffin-like (ECL) cell, is central in gastric carcinogenesis and most probably the cell of origin of gastric carcinomas of the diffuse type according to Lauren (a classification probable in accordance with biology)." (PMID 34202596, 2021). "Co-expression of gastrin and CCK2R might contribute to progression of gastric cancer." (PMID 32210918, 2020). "CCK and CCK1R might play a more important role than for gastrin and CCK2R in gastric cancers." (PMID 32210918, 2020). "Thus, in contrast to gastric NETs, gastrin has been claimed not to play any role in the development of gastric cancer." (PMID 33266504, 2020). "Nevertheless, gastrin and the ECL cell could be involved in the tumourigenesis of gastric carcinomas of intestinal type by gastrin releasing not only histamine, but also a factor like REG I which has a stimulatory effect on stem cell proliferation and thus could predispose to carcinoma development." (PMID 30567376, 2018).
gastric cancer (continued). "Elucidation of the mechanism of gastrin modulation by HB-EGF-mediated EGF receptor transactivation should facilitate the development of therapeutic strategies against H. pylori-related hypergastrinemia and consequently gastric disease development, including gastric cancers." (PMID 29379775, 2017). "Also, consistent with our results is the lack of a significant difference in serum gastrin concentrations between dogs with gastric carcinoma and healthy control dogs." (PMID 29115998, 2017). "Since the gastric carcinomas with endocrine differentiation (which mainly are of diffuse type), more specifically seem to be of ECL cell origin, the principal regulator of ECL cell function as well as growth, gastrin, naturally becomes of central interest in gastric carcinogenesis." (PMID 28144230, 2017). "However, it is true that gastrin apparently may be normal in many patients with gastric carcinoma, which could suggest that gastrin nevertheless is not central in gastric carcinogenesis." (PMID 34202596, 2021). "Growing evidence shows that in addition to the expression of gastrin in the endocrine G cells of the stomach, GASTRIN and CCK-BR genes also become overexpressed in nonendocrine gastric cancer epithelial cells." (PMID 34976177, 2022). "Both gastrin and CLU might promote cell migration/invasion, and, even though sCLU did not affect migration of AGS-GR cells, our findings do not exclude a pro-migratory role of CLU in other gastric cancer cell lines or in vivo." (PMID 28902909, 2017).